INS (insulin)
Diseases named in the same sentence as INS in open-access papers (continued):
Sharing a sentence is not in itself a finding about the gene and the disease.
diabetes (continued). "UC administration significantly reduced diabetes incidence, attenuated insulitis, elevated insulin levels and GSIS and reduced blood glucose and AUC in NOD mice." (PMID 38040681, 2023). "Improvement of glucose levels by α-lipoic acid has been previously recorded in T2DM cases through improving the diabetes-related deficit in glucose metabolism in addition to activation of insulin signaling pathways." (PMID 37139293, 2023). "The exosome-derived miR-26a increases insulin sensitivity by enhancing insulin signaling and reducing hyperinsulinemia, a typical symptom of type 2 diabetes mellitus (T2DM)." (PMID 36818396, 2023). "Diabetes and obesity are the paramount recurrent endocrine-metabolic disorders that are categorized by hyperglycemia and impaired insulin secretion and/or its action." (PMID 37089941, 2023). "The endocrinology‐focused trials centered primarily on diabetes management with insulin titration‐related applications that allowed for patients to individualize their therapy." (PMID 37476062, 2023). "Following initiation of steroid therapy for IS, the patient developed clinically apparent insulin requiring diabetes." (PMID 37689631, 2023). "A recent study showed that the order of food intake during a meal affects postprandial glucose and insulin peaks in pre-diabetes." (PMID 38140355, 2023). "Studies on the effect of early postoperative basal insulin therapy on HRQOL after KT, especially KTRs at high risk of developing post-transplant diabetes mellitus (PTDM) are missing." (PMID 37600749, 2023). "Specifically, PPAR-gamma activation, a result of PPARG gene expression, enhances glucose tolerance and insulin sensitivity in both diabetes mellitus patients and animal models of insulin resistance." (PMID 38201926, 2023). "Previous studies have reported that GLP1R gene polymorphisms are closely related to insulin secretion and response to GLP1R analogs in diabetes patients." (PMID 38131033, 2023). "Accurate real-time blood glucose prediction based on a variety of inputs, including short-acting insulin injections, has clinical implications and great potential for improving the quality of life and longevity of individuals with diabetes." (PMID 37837098, 2023). "Diabetes management behaviors, such as monitoring blood glucose levels, administering insulin and maintaining a healthy diet aim to keep blood glucose levels within acceptable levels and prevent long-term damage." (PMID 37187938, 2023). "β1-, β3-, and β6-conglutin proteins can bind to insulin in vitro, suggesting that β-conglutin proteins have potential benefits for the prevention and treatment of diabetes." (PMID 36904097, 2023). "First and foremost, insulin is a crucial hormone to treat diabetes, as discussed more in detail in the following section." (PMID 36674821, 2023). "Diabetes is a chronic metabolic disorder characterized by high blood glucose levels resulting from the body's inability to produce or effectively use insulin." (PMID 37313065, 2023). "Both global and national guidelines have evolved over the years with recommendations for timely insulin initiation in type 2 diabetes mellitus." (PMID 36650625, 2023). "The long-course glucose and insulin trajectories depicted by the obesity-diabetes model are consistent with clinical observations and capture the trend of the longitudinal glucose data of the Pima Indian tribe." (PMID 36848379, 2023). "Let-7 functions with RNA-binding proteins Lin28a/b that when is overexpressed in mice, provoking an insulin-sensitized state able to resist high-fat-diet-induced diabetes." (PMID 36674935, 2023). "In an inflammatory microenvironment, the remaining β-cells cannot satisfy the metabolic requirement of insulin generation, ultimately precipitating diabetes." (PMID 37031163, 2023). "Adiponectin concentrations are strongly related to insulin sensitivity, resulting in reduced concentrations in obese patients, obese patients with mild diabetes and obese patients with T2D." (PMID 38136211, 2023).
diabetes (continued). "Diabetes mellitus (DM) is a metabolic disorder that affects the body's ability to produce or use insulin." (PMID 37038362, 2023). "Patients with diabetes that used some type of insulin for at least three months prior to the study were interviewed, as well as their family caregivers." (PMID 37377235, 2023). "All three of the best models selected length of dialysis treatment, type of dialysis access, diabetes medication (insulin, or oral), anti-inflammatory medication, etiology of hypertension, intradialytic weight gain and heart rate." (PMID 37505893, 2023). "High iron is a risk factor for type 2 diabetes mellitus (T2DM) and affects most of its cardinal features: decreased insulin secretion, insulin resistance, and increased hepatic gluconeogenesis." (PMID 36137277, 2023). "Diabetes mellitus (DM) is a chronic metabolic disorder characterized by hyperglycemia resulting from defects in insulin secretion, insulin function or both and requires continuous medical care." (PMID 36767972, 2023). "The findings of this study on the adoption of wearable insulin biosensors among diabetes patients carry both practical and theoretical implications." (PMID 38239544, 2023). "Insulin-CAR-Tregs were unable to prevent spontaneous diabetes in NOD mice, although the cells survived long term in diabetic mice." (PMID 37593744, 2023). "Type 2 diabetes mellitus (T2DM) is a complex metabolic disease characterized by reduced peripheral tissue response to insulin (insulin resistance) coupled with inadequate insulin secretion due to β-cell dysfunction." (PMID 37813629, 2023). "Groups A and B showed more prominent reductions in TC than group C (p = 0.02), but the difference disappeared after adjusting for age, sex, diabetes type, diabetes duration and insulin therapy (p = 0.15)." (PMID 37194402, 2023). "Diabetes mellitus is a chronic endocrine condition in which the pancreas either stops producing insulin or produces inadequate insulin." (PMID 37569399, 2023). "Most people with diabetes inject insulin with a syringe or pen as the insulin delivery method; other methods of insulin delivery, including insulin inhalers, insulin pumps, or automated insulin delivery devices, are seldom used." (PMID 36782190, 2023). "A study by Silas and Tshilwane found that rats that had a comorbidity of diabetes and T. zimbabwensis infection had an increased insulin level on day 35 post-infection when compared to the diabetic group." (PMID 38139040, 2023). "A process-based TRACER assessing insulin ordering behaviors among trainees admitting patients with diabetes would have a strong evidence-based justification." (PMID 37215538, 2023). "Secretion of insulin was only observed for cells grown in medium 1 and differentiation of MSCs towards insulin-producing cells has been shown by expansion under specific growth conditions, bearing potential for treatment of diabetes." (PMID 37626914, 2023). "Diabetes mellitus is a metabolic syndrome characterized by increased glucose levels, oxidative stress, hyperlipidemia, and frequently decreased insulin levels." (PMID 36677055, 2023). "This transfer is decreased in diabetes, probably as the result of disturbed lipolysis because insulin resistance limits the activity of lipoprotein lipase." (PMID 36979432, 2023). "The usual treatment for diabetics consists in the administration of insulin delivered by injections with syringes or microneedles or by oral administration." (PMID 36771883, 2023). "Diabetes is a multifaceted chronic condition, characterized by insufficient insulin production or impaired insulin utilization, resulting in elevated blood glucose levels." (PMID 38239544, 2023). "In item 3, “Other people have told me that my eating is out of control”, some misconstrued the question as being entangled with diabetes compliance, as is also the case with item 4, “After I overeat, I don’t take enough insulin to cover the food”." (PMID 36754894, 2023).
diabetes (continued). "We additionally measured change in self-reported insulin beliefs, diabetes distress and depressive symptoms between baseline and 6-month post-randomisation." (PMID 37237318, 2023). "When insulin is not produced enough by the body or the cells fail to respond to insulin, too much blood sugar remains in the bloodstream, resulting in diabetes mellitus." (PMID 37372005, 2023). "Type 2 diabetes is characterized by resistance of the liver, adipose tissue, and the muscles to the action of insulin; it usually occurs after the age of 50 and accounts for 85–90% of diabetes." (PMID 37396152, 2023). "Subjects in the two groups were similar in age, male: female ratio, body mass index (BMI), duration of diabetes, duration of insulin use, the total daily dose of insulin, presence of comorbidities, diabetic complications, and lipodystrophy." (PMID 36782190, 2023). "Despite optimization of insulin therapy and diabetes education during hospitalization, all enrolled patients experienced post-prandial hyperglycemia." (PMID 38993859, 2023). "The examples discussed include digital twins in diabetes management, such as the artificial pancreas, which improves blood glucose monitoring and insulin administration." (PMID 37888133, 2023). "Fixed insulin doses from the onset of diabetes were taught to 47.7% of the participants and 52.3% were taught ACC." (PMID 38004219, 2023). "Diabetes is thought to promote cancer development and progression through hyperglycemia, altered insulin signaling, and excessive inflammation." (PMID 37906280, 2023). "Methylglyoxal (MGO), identified as a diabetes marker, can lead to excessive ROS, which can disrupt insulin secretion in pancreatic β cells when its concentration is increased." (PMID 37512505, 2023). "Increased expression of LIMK and p-cofilin-2 in patients with metabolic syndrome and diabetes supports the role of impaired insulin signaling in cytoskeletal/synaptic structures." (PMID 37443762, 2023). "One way in which genetics contributes to diabetes is through the regulation of insulin secretion and sensitivity." (PMID 37600709, 2023). "Considering the six patients affected by diabetes mellitus, four were in nutritional therapy whereas two were in medical treatment (one in multi-injection insulin therapy in the remission group and one in metformin treatment in the discordant group)." (PMID 37829686, 2023). "The DIGAMI (Diabetes Mellitus, Insulin Glucose Infusion in Acute Myocardial Infarction) 1 trial proved that insulin-glucose infusion followed by intensive subcutaneous insulin in 620 diabetic AMI patients improved 1- and 3.4-year survival." (PMID 37403082, 2023). "Diabetes mellitus (DM) is a chronic metabolic disorder characterized by hyperglycemia resulting from insulin secretion defects or insulin resistance." (PMID 37349778, 2023). "This study used eight different characteristics (number of pregnancies, plasma glucose level, diastolic blood pressure, sebum thickness, insulin level, BMI, diabetes pedigree function, and age) for data preprocessing." (PMID 36983587, 2023). "Over the same period, the use of insulin with ≥2 other diabetes therapies increased from 10.6% to 31.6% in men and from 8.7% to 28.0% in women." (PMID 37874829, 2023). "Prevalent comorbidities included hypertension in 80 (43%) patients, hyperlipidemia in 58 (31%), diabetes treated with oral antidiabetic therapy in 44 (24%), and diabetes treated with insulin in 32 (17%)." (PMID 38239525, 2023). "The award of the Nobel Prize in Physiology or Medicine to FG Banting and JJR Macleod in October 1923 honored the successful clinical use of insulin in patients with diabetes mellitus." (PMID 37407772, 2023). "Type 2 diabetes mellitus (T2DM) is a metabolic disease characterized by chronic hyperglycemia due to impaired insulin secretion and insulin resistance (IR)." (PMID 38102588, 2023).
diabetes (continued). "Ultimately, the development of diabetes treatments has progressed over time, starting with the fundamental discovery of insulin and advancing to the present period characterized by a more sophisticated comprehension of the disease's intricacies." (PMID 38283440, 2023). "Estimating serum insulin levels in diabetics can help determine the influence of carbohydrate loading on insulin resistance and provides scope for further study." (PMID 38143683, 2023). "STZ targets the β-cells of the pancreas due to which impaired secretion of insulin occurs, leading to the onset of diabetes mellitus." (PMID 37091893, 2023). "Effective management of diabetes requires intensive monitoring of blood glucose levels and exogenous use of insulin as necessary." (PMID 37631595, 2023). "Ketoacidosis can develop when inadequate insulin is released from the pancreas to fulfill the body's glycemic demands." (PMID 37916248, 2023). "Insulin resistance (IR) is a characteristic of Type 2 Diabetes Mellitus (T2DM) where the efficiency of insulin to absorb and utilize glucose is reduced." (PMID 37810881, 2023). "Reduction of GLUT-4 expression/localization is one of the main molecular mechanisms by which oxidative stress induces insulin resistance and promotes the development of cognitive dysfunction in diabetes mellitus." (PMID 37077347, 2023). "In the last decades, there have been major advances in the field of designing devices for glucose detection and insulin delivery for the treatment of diabetes." (PMID 36771883, 2023). "Patil and Devarajan synthesized alginate NPs consisting of insulin and nicotinamide, which are used as transfusion compounds to reduce the levels of serum glucose and increase the levels of serum insulin in rats with diabetes." (PMID 37388336, 2023). "Regarding diabetes treatments, similar to findings in a previous report, pioglitazone, metformin, and insulin sensitizers were often used." (PMID 37130431, 2023). "In our study, more than 20% of patients with diabetes shifted to insulin during hospital stay from other antidiabetic drugs, and more than 10% started insulin de novo." (PMID 36767972, 2023). "Traditionally, MET, a biguanide-derived drug, is used in the treatment of diabetes mellitus type 2 as a modulator of insulin sensitivity by decreasing hepatic gluconeogenesis and lipogenesis." (PMID 37894792, 2023). "Diabetes is a metabolic disorder that is characterized by hyperglycemia as a result of insufficient insulin secretion or inadequate response to insulin in the body." (PMID 37795357, 2023). "The majority of Endocrinologists (14/22 = 64%) have started insulin based on test results other than an OGTT or HbA1c in the diabetes range (i.e., Glucometer readings or CGM)." (PMID 37274323, 2023). "Although insulin resistance contributes to altered glucose homeostasis, current evidence shows that the direct effect of aging on diabetes is exerted through the impairment function of β-cell, resulting in decreased insulin secretion." (PMID 37424876, 2023). "Automated insulin delivery (AID) has decisively changed the diabetes care landscape for people who require intensive insulin therapy." (PMID 37751154, 2023). "Short hairpin RNA–mediated (shRNA-mediated) suppression of HNF1A in primary human pseudoislets led to blunted insulin output and dysregulated glucagon secretion after transplantation in mice, recapitulating phenotypes observed in patients with diabetes." (PMID 37943614, 2023). "Diabetes mellitus is a chronic metabolic disease characterized by elevated blood glucose levels, accompanied by defects in insulin secretion, insulin action, or both." (PMID 37761031, 2023). "Diabetes mellitus occurs when the insulin secretion function of the pancreas decreases as the body’s demand for insulin increases." (PMID 37111730, 2023). "Preclinical models of diabetes have examined the relationship between diabetes-induced hyperglycemia, hypothermia, and insulin dysfunction on p-tau." (PMID 37638180, 2023).
diabetes (continued). "The link between augmented hepatic fat content and insulin insensitivity in diabetes is well established." (PMID 38203600, 2023). "In the current study, it was noticed that fasting glucose levels (FBG) were found to be significantly higher and insulin levels significantly lower in the type 2 diabetic mellitus animals." (PMID 38202711, 2023). "Diabetes mellitus was a pre-existing condition in 24.4% of all patients, with approximately 4% receiving insulin treatment." (PMID 37779728, 2023). "The person with diabetes was fearful of taking insulin because she frequently traveled out of the country and felt like it would be a burden having to transport insulin and supplies." (PMID 37535407, 2023). "Regarding IL-10, in a study with mice presenting severe hepatic steatosis and defective insulin signal transduction plus diabetes, animals were treated with two daily doses of an IL-10 inhibitor for 5 days." (PMID 37593740, 2023). "Hypoglycemia unawareness was not dependent on age, gender, duration of diabetes, duration of insulin therapy, HbA1c, frequency of blood glucose monitoring, or microvascular complications of diabetes." (PMID 37964960, 2023). "In cancers with diabetes, high levels of insulin increase glucose uptake by cancer cells, which further promotes aerobic glycolysis for energy." (PMID 37165049, 2023). "Weight gain can be an important complication of insulin treatment in both types of diabetes and can have a significant impact on increasing cardiovascular risks." (PMID 37854735, 2023). "Participants in the VBAI group had significantly faster insulin dose optimization, improved insulin adherence and glycemic control, and decreased diabetes-related emotional distress compared with those in the standard of care group." (PMID 38039007, 2023). "Patients on insulin treatment are likely to be older with a longer duration of diabetes and uncontrolled diabetes." (PMID 36859297, 2023). "Diabetes mellitus (DM) is a chronic metabolic disorder characterized by elevated blood sugar levels due to impaired insulin secretion or action, or both." (PMID 38003449, 2023). "The BA receptor FXR is known to regulate glucose metabolism and the FXR agonist OCA, an analogue of CDCA, has been demonstrated to improve insulin sensitivity in patients with type 2 diabetes mellitus." (PMID 37760936, 2023). "While prolonged fasting increases the production and release of FGF21 to stimulate gluconeogenesis, a number of studies have shown that FGF21 administration in animals with obesity or diabetes effectively improves insulin sensitivity and glucose metabolism." (PMID 37049555, 2023). "The first studies that have investigated the possibility of achieving remission of diabetes with medical treatment have been carried out with therapeutic regimens based on insulin treatment." (PMID 37077356, 2023). "The diabetes team was seen as essential for patients receiving insulin therapy when transferred to a hospital ward and the acute pain team was often engaged with patients with ongoing pain issues." (PMID 37130684, 2023). "Diabetes mellitus is a chronic metabolic disorder characterized by impaired insulin secretion, insulin action, or both." (PMID 37025407, 2023). "Correctional insulin can be used as the sole initial management for hospital admissions of newly recognized hyperglycemia or well-controlled diabetes." (PMID 37363479, 2023). "Both insulin dependent and insulin independent skeletal muscle glucose uptake are however reduced in individuals with diabetes." (PMID 37626210, 2023). "Then, the diabetes specialist analyzed and interpreted the glucose profile and individually advised each patient regarding diet, lifestyle, and insulin regimen." (PMID 37629520, 2023). "The three most important features affecting THZ-related uric acid rise include having uncontrolled diabetes, lower eGFR, and the existence of insulin at the time of “THZ action”." (PMID 38274913, 2023).